DYRK1A (dual specificity tyrosine phosphorylation regulated kinase 1A)
Diseases named in the same sentence as DYRK1A in open-access papers (continued):
Sharing a sentence is not in itself a finding about the gene and the disease.
Down syndrome (continued). "Tight regulation of DYRK1A is critical for neural development and cognitive function, and DYRK1A overexpressed in individuals with Down’s syndrome due to the extra copy of chromosome 21 is believed to underlie the pathogenesis of neurodevelopmental delay, motor abnormalities, and cognitive deficits." (PMID 30910997, 2019). "DYRK1A has attracted attention as a target for normalizing the phenotype of Down syndrome." (PMID 30760866, 2019). "dyrk1a gene is located within the Down syndrome (DS) critical region on the human chromosome 21." (PMID 31766108, 2019). "Dyrk1A decreases Notch signaling which may contribute to abnormal brain development in animal models of Down syndrome." (PMID 29587359, 2018). "Over-expression of DYRK1A in mice has been reported to mimic Down syndrome splicing aberrations." (PMID 29584757, 2018). "Taken together, similar to the situation of Down syndrome, DYRK1A with overexpressed state, but not deficiency, leads to abnormality of PGCs, depending on its PKc conserved domain." (PMID 29127398, 2017). "DYRK1A gene in human maps to the Down syndrome critical region q22.2 of chromosome 218–12." (PMID 29127398, 2017). "Dual-specificity tyrosine phosphorylation-regulated kinase 1A, or DYRK1A, is a highly conserved gene in the Down syndrome critical region of chromosome 21, and appears to play a major role in brain development, specifically neurogenesis, neural plasticity, and cellular death." (PMID 29034068, 2017). "In addition, the DYRK1A gene is situated in the Down’s syndrome (DS) critical region on chromosome 21 (21q22.1–22.3), is over-expressed in both foetal and adult brains of DS individuals and is thought to contribute to the clinical features of Down’s syndrome." (PMID 26346493, 2016). "DYRK1A is located within the Down Syndrome Critical Region on chromosome 21." (PMID 26136701, 2015). "We speculate that increased DYRK1A gene dosage (as observed in Down syndrome patients) results in reduced β-cell proliferation and an increased risk of diabetes." (PMID 26496802, 2015). "Interestingly, DYRK1A is localized within the Down Syndrome critical region (DSCR) on chromosome 21, and is considered to be a strong candidate gene for this genetic disorder." (PMID 24901999, 2014). "The evaluation of these molecules as inhibitors on a mammalian kinases panel revealed that several compounds (5, 6, 10 and 11) exhibit marked activities against CDK5, CK1 and DYRK1A, a set of kinases involved in several neuronal pathologies such as Down Syndrome and Alzheimer’s disease." (PMID 25251193, 2014). "Considering the known role of PAI-1 in cell migration, inhibition of the NFAT-mediated regulation of PAI-1 through DYRK1A overexpression could be involved in the abnormal neuronal migration in Down syndrome." (PMID 23825664, 2013). "Studies in Down syndrome mouse models overexpressing DYRK1A will be needed to assess whether these mechanism are also operative in vivo in the intact brain." (PMID 23825664, 2013). "The DYRK1A gene is located within the Down Syndrome Critical Region (DSCR) on chromosome 21." (PMID 21573099, 2011). "Studies in cell culture models and transgenic models of Down syndrome that overexpress DYRK1A implicate the DYRK1A kinase in the generation of both amyloid and tau pathologies associated with the early onset Alzheimer's disease (AD) that is uniformly observed in Down Syndrome." (PMID 21573099, 2011). "Our results might give clues to understand the protective effect of Down syndrome against vascular defect through a decrease of homocysteine level by DYRK1A over-expression." (PMID 19844572, 2009). "DYRK1A levels in the brains of DS subjects with free trisomy were found approximately 1.5-fold higher than those in normal subjects indicating that this protein is overproduced in a gene dosage-dependent manner in Down syndrome." (PMID 19242551, 2009).
Down syndrome (continued). "Furthermore, DYRK1A, a human homolog of mnb, has been mapped within the Down's syndrome critical region of chromosome 21 and is over-expressed in Down's syndrome embryonic brain." (PMID 19265526, 2009). "Similar phenotypes have been also detected in trisomy Down syndrome mouse models bearing Dyrk1A." (PMID 18648535, 2008). "DYRK1A is a candidate gene for Down syndrome localized on the human chromosome 21q22.2 region." (PMID 18648535, 2008). "Notably, DYRK1A maps to a critical region for Down Syndrome (DS) in humans and over-expression of Dyrk1a in mice has been reported to cause DS-like neurological defects." (PMID 16759393, 2006). "Thus, it remains to be seen whether overexpression of DYRK1A in people with Down syndrome can overcome the downregulation of ACE2 by SARS-CoV-2 infection." (PMID 38540156, 2024). "In addition, our findings are based on the experiments conducted with overexpressed immortalized cell lines; therefore, the observed results may not precisely represent the role of FAM53C in the impact of the DYRK1A dosage effect in Down syndrome." (PMID 37802655, 2023). "The Dyrk1a gene maps in the Down syndrome critical region, and recurrent respiratory infections are observed in patients, suggesting the possibility that deregulated Dyrk1a expression may have an impact on multiciliogenesis and/or cilia function in the respiratory tract." (PMID 34787650, 2022). "However, it is broadly recognized that DYRK1A is a good therapeutic target for Down syndrome 9,17." (PMID 33633179, 2021). "The DYRK1A gene is localized on human chromosome 21, and substantial evidence supports the hypothesis that DYRK1A overexpression significantly contributes to the altered brain development and intellectual disability in individuals with Down syndrome." (PMID 33339338, 2020). "Additionally, a recent research has demonstrated that this flavonoid improves cognitive performance and adaptive functionality in individuals diagnosed with Down syndrome by modulating the overexpression of the dual specificity tyrosine phosphorylation regulated kinase 1A (Dyrk1A)." (PMID 32438698, 2020). "Moreover, in the case of DYRK1A, over-expression can also be deleterious: the gene is located in the Down syndrome (DS) critical region and its copy number alteration may be the underlying mechanism for abnormal brain development in DS107." (PMID 28733602, 2017). "Indeed, the results of this assay suggest that DYRK1A inhibitors could be used to ameliorate neural phenotypes in Down syndrome, though clearly the dose of the agents would need to be controlled rather precisely to avoid excessive reduction in enzyme activity." (PMID 28884684, 2017). "Nevertheless, given that the blood PAI-1 levels in Down syndrome individuals are lower than in controls we hypothesize that the attenuation of the NGF-induced PAI-1 by overexpression of DYRK1A and RCAN1 due to trisomy 21 may be relevant to several Down syndrome features." (PMID 23825664, 2013). "In Down syndrome, the presence of three copies of chromosome 21 leads to overexpression of key genes, including APP and DYRK1A." (PMID 41465426, 2025). "The overexpression of HSA21 genes like DYRK1A, PDE9A, PCP4, and PCNT in Down syndrome disrupts calcium homeostasis, primarily by suppressing the calcineurin pathway." (PMID 41274866, 2025). "Dual-specificity tyrosine phosphorylation-regulated kinase 1A (DYRK1A), a protein kinase that is preserved across evolutionary scales, plays a crucial role in the onset of Down syndrome and other diseases." (PMID 38139175, 2023). "Dual-specificity tyrosine phosphorylation-regulated kinase 1A (DYRK1A), located in the Down’s syndrome critical region, plays pivotal roles in neurodegenerative diseases, such as Alzheimer’s disease and Down’s syndrome." (PMID 35655269, 2022).
Down syndrome (continued). "Our findings on the collaborative role of CEP97 and Dyrk1a in multiciliation may add to our existing knowledge regarding pericentrin overexpression in patients with trisomy 21 and therapeutic approaches for the respiratory diseases in patients with ciliopathy and Down syndrome." (PMID 34787650, 2022). "Another DYRK1A inhibitor, green tea flavonol epigallocatechin-gallate (EGCG), was shown to correct cognitive deficits in Down Syndrome mouse models and humans." (PMID 34445786, 2021). "However, it is worth noting that the development of DYRK1A inhibitors may be beneficial in the treatment of other diseases, including neurological disorders such as Alzheimer’s Disease(AD), Parkinson’s and Huntington’s diseases, Down Syndrome (DS) and cancer." (PMID 34445786, 2021). "Neurogenesis-related genes such as DYRK1A and RCAN1, craniofacial defect-related genes such as DYRK1A, ETS2, and RCAN1, and tumor suppressor-related genes such as DYRK1A, ETS2, and RCAN1 were also reported in Down syndrome." (PMID 34433490, 2021). "DYRK proteins are homologous to the Drosophila minibrain gene, and DYRK1A is widely known for its role in Down syndrome (DS)." (PMID 31035417, 2019). "Expression levels of Down syndrome-related genes such as SOD1, DYRK1A, ETS2, APP, and DSCR1 in chromosome 21 are comparable with the gene number, i.e., three 21 chromosomes." (PMID 30760866, 2019). "Nevertheless, both mouse models carry most of the gene complement of the Down syndrome critical region, including RCAN1, APP, SOD1 and DYRK1A." (PMID 30034324, 2018). "Patients with Down syndrome (trisomy 21) have increased gene dosage of genes in the Down syndrome critical region (DSCR), which includes DYRK1A." (PMID 26496802, 2015). "Genetic studies demonstrate increased gene dosage of Dyrk1a and another gene in the DSCR (DSCR1) combine to reduce NFAT signalling leading to Down syndrome-like features in mice." (PMID 26496802, 2015). "Extending our data on DYRK1A, actin and MAL/SRF, publicly available array data of human Down syndrome patient brain tissue demonstrate a reduced expression of numerous MKL1/SRF target genes." (PMID 26310823, 2015). "Several DYRK1A inhibitors have shown promise for improving cognition in rodent models of Down syndrome and Alzheimer's disease, for example, but the ability to affect DYRK1A levels or activity in relevant human cells has not been established." (PMID 41676546, 2026). "While higher DYRK1A expression levels are expected in ALL cells from patients with Down syndrome, given that DYRK1A is located on chromosome 21, it is not known how DYRK1A is transcriptionally regulated." (PMID 40148558, 2025). "A previous pilot study demonstrated that EGCG, an inhibitor of dual-specificity tyrosine-(Y)-phosphorylation regulated kinase 1A (DYRK1A), administered to young patients with Down syndrome improved visual recognition memory, working memory performance, and adaptive behavior." (PMID 40807299, 2025). "The experiments showed that the prepared biosensor achieved an ultra-sensitive and specific detection of the DYRK1A gene in the range of 10 aM–100 pM, indicating that the MoS2/WTe2 FET biosensor has great application potential in the prenatal screening of Down syndrome." (PMID 38276744, 2024). "It is known that increased DYRK1A expression impacts the splicing of TNNT2 and the proportion of cTnT transcript variants in hearts from a mouse model of Down syndrome and in human non-cardiac cells." (PMID 35596909, 2022). "Perhaps for this reason, DYRK1A inhibitors have not reached the clinic for children with Down Syndrome." (PMID 34335466, 2021). "Recent studies have demonstrated that some DYRK1A inhibitors such as the antioxidant Epigallocatechin gallate (EGCG) improve long-term outcomes related with memory and executive function in individuals with Down syndrome." (PMID 32760684, 2020).
Down syndrome (continued). "Taken together, DYRK1A and RCAN1 can act synergistically to block NFAT-dependent transcription, suggesting that the reduced NFAT activity resulting from the 1.5-fold overexpression of DYRK1A and RCAN1 could be the basis of many features of Down syndrome." (PMID 23825664, 2013). "In animal models, when NRON was removed from the regulation of DSCR1 and DYRK1A genes on chromosome 21, the expressions of DSCR1 and DYRK1A were upregulated, leading to the decrease of NFATc activity, which eventually resulted in characteristics of Down syndrome (DS)." (PMID 33791072, 2021). "Besides, except for Down syndrome patients, DYRK1A overexpression may not occur in other AD patients." (PMID 41513640, 2026). "The authors concluded that the negative effect of DYRK1A and RCAN1 overexpression on NGF signal transduction in neural cells may contribute to the altered neurodevelopment and brain function in Down syndrome." (PMID 29342922, 2018).
Alzheimer disease (74 papers, 2009 to 2026). A progressive, neurodegenerative disease characterized by loss of function and death of nerve cells in several areas of the brain leading to loss of cognitive function such as memory and language. "In summary, DYRK1A overexpression in T21 has been associated with many neurodevelopmental, behavioral and neurodegenerative alterations, including DS-related Alzheimer’s disease (DS-AD)." (PMID 40519271, 2025). "The development of pharmacological inhibitors of DYRK1A is a major avenue for the treatment of cognitive deficits associated with DS (and Alzheimer’s disease) (reviews:)." (PMID 34205123, 2021). "Chr21 contains approximately 233 protein-coding genes, some of which, like amyloid precursor protein (APP) and dual-specificity tyrosine phosphorylation-regulated kinase 1A (DYRK1A), have been linked to an Alzheimer’s disease (AD)-like phenotype." (PMID 33660221, 2021). "DYRK1A has also been implicated in tau protein phosphorylation in the pathogenesis of Alzheimer’s disease." (PMID 28884684, 2017). "HQSAR (2D fragment-based) models were developed for 46 6-arylquinazolin-4-amines (N training = 36; N test = 10), a series of inhibitors for DYRK1A, an enzyme associated with Alzheimer’s disease." (PMID 25756379, 2015). "We also focus on GSK3β and DYRK1A, markers of Alzheimer’s disease, which are also closely associated with pancreatic β-cell dysfunction and type 2 diabetes, and thus may represent common therapeutic targets for both diseases." (PMID 36499613, 2022). "Moreover, through hyperphosphorylation of tau protein (Alzheimer’s Disease protein) and the formation of insoluble tau aggregates, DYRK1A is also involved in neurodegeneration and neuronal loss appearing in AD." (PMID 34445786, 2021). "As dual-specificity tyrosine phosphorylation-regulated kinase 1A (DYRK1A) has been implicated in the abnormal hyperphosphorylation of tau in Alzheimer's disease (AD) brain, and the development of neurofibrillary tangles, we examined the contribution of this gene to the susceptibility for AD." (PMID 19995442, 2009). "A clinical casein kinase 2 inhibitor, CX-4945 (silmitasertib),shows significant affinity toward the DYRK1A and GSK3β kinases,involved in down syndrome phenotypes, Alzheimer’s disease,circadian clock regulation, and diabetes." (PMID 36883902, 2023). "Recently, harmine derivatives were identified as GSK-3β/DYRK1A dual inhibitors, thereby serving as potent candidates for Alzheimer’s disease." (PMID 36877059, 2023). "Dyrk1A is an important factor contributing to intellectual disability, memory deficit and Alzheimer's disease (AD)‐type dementia, the main features of the DS phenotypes." (PMID 37415307, 2023). "We previously showed that individuals with Alzheimer’s disease have decreased plasma DYRK1A levels compared to controls." (PMID 37015911, 2023). "DYRK1A is a potential therapeutic target for many diseases including Down Syndrome (DS), Alzheimer’s disease (AD) and Parkinson’s disease (PD)." (PMID 36676976, 2022). "Harmine derivatives were also optimized as potent GSK-3β/DYRK1A dual inhibitors for the treatment of Alzheimer’s disease." (PMID 35335117, 2022). "The discovery of selective and potent inhibitors of DYRK1A is an emerging field of investigation, as decades of research on neurodegenerative diseases, especially Alzheimer’s Disease, have recognized DYRK1A as a novel drug target for therapeutic intervention." (PMID 35208955, 2022). "The dual-specificity tyrosine phosphorylation-regulated kinase 1A (DYRK1A) is a novel, promising and emerging biological target for therapeutic intervention in neurodegenerative diseases, especially in Alzheimer’s disease (AD)." (PMID 35208955, 2022). "The expression levels of the genes for APP (Alzheimer’s disease marker), DYRK1A, DSCR1 (Down syndrome critical region 1), ETS2, and SOD1, all of which are located on chromosome 21, are dysregulated in trisomic cells." (PMID 34433490, 2021).